GOLT1A (golgi transport 1A)
Description:
May be involved in fusion of ER-derived transport vesicles with the Golgi complex.
Synonyms: GOT1B; FLJ42654; CGI-141; YMR292W; GOT1; MGC62027; HMFN1187; hGOT1b
Tractability: Antibody: UniProt predicts a signal peptide or a membrane-spanning region. PROTAC: its protein half-life has been measured.
Gene: Protein-coding gene on chromosome 1 (204,198,158 to 204,214,121, reverse strand). Ensembl gene ENSG00000174567.
Subcellular location: Golgi apparatus membrane
Gene Ontology:
Molecular function: protein binding
Biological process: endoplasmic reticulum to Golgi vesicle-mediated transport; retrograde transport, endosome to Golgi; vesicle-mediated transport
Cellular component: endoplasmic reticulum; Golgi cis cisterna; nuclear envelope; trans-Golgi network; membrane; cytoplasm; cytosol; endomembrane system; Golgi membrane
Genetic constraint (gnomAD): Loss-of-function variants: 9 observed, 14.77 expected, observed/expected ratio (o/e) 0.61, 90% interval 0.37 to 1.06. The upper end of that interval is the gene's LOEUF score, 1.06, which puts it in group 4 of 6, group 1 being the genes least tolerant of losing a copy. Missense variants: 131 observed, 163.61 expected, observed/expected ratio (o/e) 0.8, 90% interval 0.69 to 0.93. Synonymous variants: 57 observed, 66.18 expected, observed/expected ratio (o/e) 0.86, 90% interval 0.69 to 1.07.
Homologues: Orthologues: chimpanzee GOLT1A (99% identical), pig GOLT1A (92% identical), mouse Golt1a (86% identical), guinea pig GOLT1A (86% identical), dog GOLT1A (85% identical), rat Golt1a (83% identical), macaque GOLT1A (71% identical), zebrafish golt1a (68% identical), Drosophila melanogaster CG32576 (56% identical), Caenorhabditis elegans Y54G2A.45 (11% identical), Caenorhabditis elegans C39B5.14 (11% identical), Caenorhabditis elegans Y49E10.25 (11% identical), and 20 more. Paralogues in human: GOLT1B (57% identical), DAGLA (26% identical), DAGLB (23% identical).
Diseases named in the same sentence as GOLT1A in open-access papers:
GOLT1A is named in the same sentence as 10 diseases in open-access papers, as found by Europe PMC text mining. Sharing a sentence is not in itself a finding about the gene and the disease. The quoted sentences say what the papers report.
breast carcinoma (10 papers, 2015 to 2024). "GOLT1A, a Golgi transport homolog, is overexpressed in breast cancer, and low expression is associated with good prognosis." (PMID 34804955, 2021). "For example, GOLT1A knockdown restored tamoxifen sensitivity in TamR cell; low GOLT1A expression was associated with good prognosis for breast cancer." (PMID 28968955, 2017). "Of note, we found that low GOLT1A expression was associated with good prognosis for breast cancer in a breast cancer microarray dataset." (PMID 26255816, 2015). "Studies have shown that golgi vesicle transporter 1A (GOLT1A), another member of golgi vesicle transporter family, affects tamoxifen sensitivity in breast cancer and promotes cell proliferation in lung cancer." (PMID 35127514, 2021). "According to Kazuhiro, miR-378a-3p regulates tamoxifen sensitivity in breast cancer MCF-7 cells via targeting GOLT1A." (PMID 34630565, 2021). "Two datasets indicated that GOLT1A was substantially overexpressed (by > 2-fold) in clinical breast cancers compared to normal breast tissues (P < 1e-8)." (PMID 26255816, 2015). "GOLT1A was overexpressed in breast cancer specimens and GOLT1A-specific siRNAs inhibited the growth of TamR cells." (PMID 26255816, 2015). "Low GOLT1A levels were also shown to be correlated with better survival in patients with breast cancer." (PMID 26255816, 2015). "For example, lidocaine increases the sensitivity of breast cancer cells to tamoxifen by down-regulating the expression of GOLT1A, which enhanced prognosis, Lidocaine also enhances the toxicity of the cancer drugs mitomycin C, pirarubicin, softening lotion and cisplatin." (PMID 34950031, 2021). "Notably, GOLT1A also modulates the sensitivity of breast cancer cells to tamoxifen and improved prognosis." (PMID 34950031, 2021). "It remains to be investigated whether new inhibitors for the ER-to-Golgi network can manage tamoxifen-resistant breast cancers, particularly those with high expression of GOLT1A and with altered ER-to-Golgi network." (PMID 26255816, 2015). "Low GOLT1A levels were correlated with better survival in patients with breast cancer." (PMID 26255816, 2015). "Moreover, the examination of publicly available microarray datasets revealed that high levels of GOLT1A expression correlated with poor rates of survival for patients with breast cancer." (PMID 26255816, 2015). "Since GOLT1A was shown as a candidate miR-378a-3p target in breast cancer cells, we investigated whether a negative correlation between miR-378a-3p and GOLT1A expression can be observed in clinical breast cancer specimens." (PMID 26255816, 2015).
lung carcinoma (3 papers, 2021 to 2022). "The proliferation of lung cancer cells can be repressed by lidocaine via decreasing GOLT1A generation." (PMID 34249706, 2021). "Lidocaine inhibits the proliferation of lung cancer cells via repressing the GOLT1A expression." (PMID 34249706, 2021).
colorectal adenocarcinoma (1 paper, 2021). The most common type of colorectal carcinoma. "Differential gene expression analysis showed distinct gene expression patterns in GCA compared to colorectal adenocarcinoma, with a number of cancer-related differentially expressed genes, including upregulation of TMEM14A, GOLT1A, DSCC1, and HSD17B8, and downregulation of KCNQ1OT1 and MXRA5." (PMID 34804955, 2021).
colorectal cancer (1 paper, 2024). A primary or metastatic malignant neoplasm that affects the colon or rectum. "GOLT1A has been reported to be differentially expressed between high and low risk groups for esophageal cancer and RAB27B is a significant prognostic marker for metastasis and poor prognosis in colorectal cancer." (PMID 38632500, 2024).
lung adenocarcinoma (1 paper, 2022). A carcinoma that arises from the lung and is characterized by the presence of malignant glandular epithelial cells. "GOLT1A was significantly elevated in patients with lung adenocarcinoma and was related to poor prognosis and adverse pathological stage." (PMID 35252243, 2022).
squamous cell carcinoma (1 paper, 2023). A carcinoma arising from squamous epithelial cells. "This comparison showed an overlap of five genes (ETV4 (tumor non-malignant signature), STK32A, SPINK1, GOLT1A, KRT6A (adenocarcinomas—squamous cell carcinomas signature)) in the first case, and an overlap in one (KRT15) of the three most prominent genes in the second case." (PMID 36832225, 2023).
cancer (4 papers, 2021 to 2025). A tumor composed of atypical neoplastic, often pleomorphic cells that invade other tissues. "Circ_PDZD8 has been shown to alleviate lidocaine’s inhibitory effect on malignant tumor cells by regulating the miR-516b-5p/GOLT1A axis (Zi, Chen & Ruan, 2022)." (PMID 39790460, 2025).
GOLT1A also shares sentences with these, for which no sentence is quoted: tumor (3 papers); adenocarcinoma (1); esophageal cancer (1).